IL18 (interleukin 18)
Diseases named in the same sentence as IL18 in open-access papers (continued):
Sharing a sentence is not in itself a finding about the gene and the disease.
tumor (continued). "Cytokines such as Interleukin (IL) 12 and IL18 have been applied to increase cellular immunity and reduce angiogenesis in neoplasms and were shown to have synergistic antitumoral effects." (PMID 25967290, 2015). "For example, IL-18 produced by immune cells has an anti-tumor activity; however, IL-18 produced by tumor cells has an important role in the immune escape process." (PMID 25992978, 2015). "In this study, we successfully enhanced the effects of GM-CSF on CT26 tumor cells by co-expression with membrane-bound IL-18." (PMID 26186692, 2015). "Combination therapies of IL-18 with granulocyte-macrophage colony-stimulating factor can facilitate tumor antigen presentation and induce proliferation of tumor-specific T cells." (PMID 25591548, 2015). "In this study, we expressed membrane-bound granulocyte-macrophage colony-stimulating factor (GM-CSF) and interleukin-18 (IL-18) as adjuvants in tumor cells to stimulate immune response." (PMID 26186692, 2015). "In combination with other interleukins, such as IL-12 and IL-15, IL-18 can be used to pre-activate NK cells with anti-tumour functions." (PMID 24778454, 2014). "The role of IL-18 as a pro- or anti-tumour agent has been discussed in the literature and seems greatly dependent on the cancer cell type." (PMID 24778454, 2014). "Among the up-regulated genes that encode secreted factors, we selected the pro-inflammatory cytokine IL-18 as it participates in tumour growth and metastasis formation." (PMID 24778454, 2014). "ATP release will induce P2RX7, which will cause the activation of NLRP3 on dermal APCs, eliciting the production of IL-1β and IL-18 which has been shown to decrease the tumor responsiveness to certain vaccinations." (PMID 24949488, 2014). "Haptenation will also cause keratinocytes to release IL-1β, IL-6, IL-18, and TNFα, which have been shown to cause MDSC recruitment and infiltration at the tumor site, subsequently causing IL-10 release and immune suppression." (PMID 24949488, 2014). "Our findings indicate that, in patients with T-ALL (and also in T-ALL xenograft models), IL-18 production is enhanced and it acts as a tumour cell proliferative factor." (PMID 24778454, 2014). "IL-18, formerly known as interferon-γ inducing factor, is a pleiotropic, proinflammatory cytokine with dual effects on tumor development and progression." (PMID 24963217, 2014). "IL-18 gene therapy alone was successful with a small-volume inoculation of tumor cells; but, in the present study, 10-fold the number of tumor cells was inoculated, and tumors grew progressively after IL-18 gene therapy by itself." (PMID 25051201, 2014). "In this context, our previous data showed that co-expression of IL-12 plus IL-18 cDNA achieved strong anti-tumor effects, similar to IL-12 cDNA alone, along with a significant increase in survival." (PMID 24587231, 2014). "To confirm the importance of the mannoprotein fraction, we also demonstrate that blocking the mannose receptor decreases the effect of C. albicans and its mannoproteins, inhibiting IL-18 synthesis and tumor cell adhesion increase by around 60%." (PMID 23301091, 2013). "S. Typhimurium has been used in several murine trials examining immunotherapies, with significant tumour reduction resulting from local bacterial expression or tumour cell expression of the immune-stimulating molecules IL-18, CCL21, LIGHT or Fas ligand." (PMID 23537317, 2013). "The inhibition of inflammasomes or neutralization of their products, mainly IL-1β, and IL-18, has profound effects on carcinogenesis and tumor progression." (PMID 23940760, 2013). "In contrast, IL-18 enhances NK cell activity, reduces tumorigenesis, induces apoptosis and inhibits angiogenesis in tumor cells to exert anti-tumor effects." (PMID 24223129, 2013).
tumor (continued). "Specifically, it has been reported that malignant cancer cells increase their adherence to microvascular wall and even promote production of angiogenic and tumor growth-stimulating factor through the IL-18-dependendent pathway." (PMID 24349532, 2013). "IL-18 can stimulate natural killer cells and T cells promoting primarily Th1 response, which is able to increase the immune defense against tumor cells by activating and inducing the production of IFN-γ." (PMID 24066061, 2013). "Although discussed in detail later in this review, IL-18’s protective effects include the ability to induce cell death and tumor regression through NK cell activation." (PMID 23847622, 2013). "By contrast, LF has also been demonstrated to inhibit tumour-initiated angiogenesis in vitro and in vivo, possibly by blocking endothelial function and inducing IL-18 production." (PMID 23761817, 2013). "IL-18 exerts its anti-tumor activity by inducing cell cycle arrest for DNA repair, promoting cytotoxic cells activity, and triggering mutated cells apoptosis." (PMID 24349532, 2013). "Tumor-promoting inflammation is driven by many factors including the presence of the pro-inflammatory cytokines interleukin (IL)-1β and IL-18." (PMID 24273542, 2013). "Strong cellular immune response was observed following infiltration of the MSCs in the tumor stroma, and resistance of the surviving animals to tumor re-challenge was observed in the studies using IL-12 and IL-18." (PMID 24202446, 2013). "And these results support the view that the expression of activation markers and the acquisition of cytotoxicity of NK cell against tumor cells required IL-18 and IL-12 released from macrophages." (PMID 22629344, 2012). "Tumor growth, metastasis, body weight, and levels of interleukin 18 (IL-18) and interferon γ (IFN-γ) were analyzed." (PMID 23231648, 2012). "These Kit+ NK cells accumulated in primary and secondary lymphoid organs of tumor bearers in an IL-18-dependent fashion." (PMID 23269924, 2012). "Although both approaches in delivering IL-18 inhibited tumor growth, the mechanisms of action are seemingly different." (PMID 21935389, 2011). "In those studies, the anti-tumor effects of IL-18 were mediated through enhancement of anti-tumor immunity or inhibition of tumor angiogenesis." (PMID 21935389, 2011). "IL-18 significantly inhibited the growth of both subcutaneous and orthotopic RM1 tumors and the IL-18 neutralizing antibody abrogated the tumor growth-inhibition." (PMID 21935389, 2011). "In previous studies, numerous mechanisms have been shown to be involved in mediating the anti-tumor effects of IL-18." (PMID 21935389, 2011). "In mice implanted subcutaneously with the control cell line, RM1-LACZ, IL-18 neutralization resulted in significantly larger tumors (p = 0.0477), suggesting that endogenous IL-18 plays a role in tumor immunity." (PMID 21935389, 2011). "The anti-tumor effect was dependent on IFN-γ as inactivation of this cytokine rendered IL-18 incapable of inducing tumor stasis." (PMID 21935389, 2011). "The anti-tumor effect is mediated by induction of IFN-γ expression by IL-18, resulting in stimulation of both the innate and adaptive immune." (PMID 21935389, 2011). "IL-18 gene-transfer into tumor cells, alone or in combination with IL-12 or IL-23, results in tumor growth inhibition." (PMID 21935389, 2011). "Of interest also is the observation that neutralization of endogenous IL-18 allows tumors to grow more rapidly indicating that in this model IL-18 is important for tumor immune surveillance." (PMID 21935389, 2011). "To reveal the significance of time-dependent drug properties in the interactions between IL-18 and chemotherapy, we tested the combinations of IL-18 with carboplatin or gemcitabine, two chemotherapeutic drugs that kill tumor cells in a dose-dependent manner." (PMID 21609494, 2011).
tumor (continued). "IL-18-mediated tumor stasis is also achieved by administrating the cytokine via intraperitoneal, intravenous, intratumoral and peritumoral routes." (PMID 21935389, 2011). "Chemotherapy treatment was started 2 weeks after tumor inoculation, while IL-18 treatment was started 2 days after initiation of chemotherapy." (PMID 21609494, 2011). "As a single agent, IL-18 was shown to elicit anti-tumor reactivity when administered at high doses in mice with established tumors." (PMID 21609494, 2011). "An involvement of macrophages in the anti-tumour effect of IL-18 is further supported by the finding that intratumoral injection of rIL-18 into subcutaneous tumours elevated serum levels of MCP-1." (PMID 21935389, 2011). "Tumor immunotherapy with IL-18 can significantly augment the killing fraction of phase-specific chemotherapeutic drugs and provide survival benefit." (PMID 21609494, 2011). "IL-18 only inhibited tumor growth when administered directly into the tumor mass (intralesional) or if the cytokine was secreted by tumor cells." (PMID 21935389, 2011). "The results presented here clearly demonstrate that for intraprostatic tumors the anti-tumor effects of IL-18 are primarily mediated through IFN-γ because neutralization of IFN-γ completely abolished IL-18-mediated protection." (PMID 21935389, 2011). "In phase I clinical evaluation, recombinant human (rh)IL-18 was safely administered as monotherapy to 28 patients with solid tumors, with minimal dose-limiting toxicities and two partial tumor responses." (PMID 21609494, 2011). "This demonstrates an important role for adaptive immunity in mediating the anti-tumor effects of IL-18." (PMID 21935389, 2011). "Because of this, we employed intraprostatic implantation of RM1 cells in further experiments to investigate the anti-tumor mechanisms induced by IL-18 in the prostate." (PMID 21935389, 2011). "Il18 has an important and complex role in inflammatory and immune responses; it has been reported to have both tumor-promoting and anti-tumor activities in different contexts." (PMID 21244661, 2011). "The reported mechanisms of action of IL-18-induced anti-tumor immunity in previous studies have varied." (PMID 21935389, 2011). "Profound tumor-infiltration of macrophages was observed in the Ctrl treatment group, but less so when IL-18 was inactivated." (PMID 21935389, 2011). "IL-18 as an adjuvant enhances the anti-tumor efficacy of dendritic cell-based vaccines and suicide gene therapies." (PMID 21935389, 2011). "Previously, we showed that the pro-adhesive effect of IL-18 on tumor-activated HSE cells was VEGF-dependent." (PMID 21569399, 2011). "All mice implanted with RM1-IL18 tumor cells orthotopically (in the prostate) developed tumors, however, neutralization of IL-18 through αIL-18 treatment resulted in significantly larger tumors (p<0.001)." (PMID 21935389, 2011). "This suggests that IL-18-independent pathways were also operating in the induction of IFN-gamma secretion during tumor metastasis development in this model." (PMID 21569399, 2011). "Chemotherapy treatment was started 8 days following tumor inoculation and IL-18 treatment was started 2 days later." (PMID 21609494, 2011). "In vivo neutralization of interferon-gamma (IFN-γ) completely eliminated the anti-tumor effects of IL-18 confirming an essential role of IFN-γ as a down-stream mediator of the anti-tumor activity of IL-18." (PMID 21935389, 2011). "Improved tumor control by combination therapy is presumed to be mediated through the amalgamation of IL-18 mediated immune activation, with Doxil-mediated tumoricidal activity and increased immunogenicity of the surviving tumor cell fraction in vivo." (PMID 20003308, 2009). "Combination IL-18 and Doxil significantly suppressed tumor growth compared with either monotherapy in vivo and uniquely resulted in complete tumor regression and long term antitumor protection in a significant proportion of mice." (PMID 20003308, 2009).
tumor (continued). "In mice, IL-18 promotes protection against tumor challenge, and enhances NK cell cytotoxocity and T cell effector function." (PMID 20003308, 2009). "In phase I evaluation, recombinant human (rh)IL-18 monotherapy has been safely administered to 28 patients with solid tumors, with two partial tumor responses." (PMID 20003308, 2009). "In conclusion, we provide evidence that Doxil favorably alters the immunophenotype of cancer cells that survive direct killing allowing for increased tumor killing by IL-18 immunotherapy in vivo." (PMID 20003308, 2009). "The combination of IL-18 with Doxil at doses below the maximally tolerated dose substantially restricted tumor growth in comparison with Doxil or IL-18 monotherapy." (PMID 20003308, 2009). "For example, tumor-produced IL-18 induces Fas ligand expression in melanoma cells, possibly resulting in escape from NK cell-mediated immune surveillance." (PMID 18818761, 2008). "In this study, we validate the antitumoral efficacy of mIL-18 overexpression in CT26 tumor-bearing mice by using plasmid vectors to transfer the mouse IL-18 gene alone." (PMID 17519043, 2007). "Plasmid vectors encoding IL-18 were transferred directly into the liver 7 days after tumor injection to restrict IL-18 expression within the tumor site." (PMID 17519043, 2007). "IL-18 exhibits context-dependent immunoregulatory characteristics (acting as a "context resistor") during tumor occurrence and progression, which is closely related to cancer type, stage, and the signaling network of the tumor microenvironment." (PMID 41751464, 2026). "The tumor microenvironment can also be modulated by cytokines and/or cellular vaccines such as modified dendritic cells that overproduce IL-12, IL-15/IL-15Rα, and IL-18." (PMID 41846923, 2026). "The evaluation of inducible or tumor-selective IL-18 deployment will show whether it is possible to minimize IL-18 related systemic toxicities while preserving localized amplification of anti-tumor activity." (PMID 41728085, 2026). "These dichotomous effects underscore the complex therapeutic implications of IL-18 in oncology, necessitating further investigation into its context-dependent mechanisms within distinct tumour microenvironments and comprehensive evaluation of its feasibility as a therapeutic target." (PMID 40738927, 2025). "Additionally, CAR-T cells engineered to release IL-18 successfully modulated the tumor microenvironment, significantly enhancing their in vivo expansion, persistence, and survival." (PMID 40861448, 2025). "On the anti-tumor side, IL18 activates natural killer cells and promotes Th1 responses." (PMID 41257666, 2025). "In addition to IL-12, IL-18, which is expressed by different immune cells, including DCs, also has anti-tumor activity." (PMID 40497988, 2025). "Using the MC38 mouse tumor model, we screened an array of IL-18 variants fused to anti-mPD-1 (RMP1-14) and identified an optimal IL-18 variant which, relative to wild type mouse IL-18, is ~10,000-fold attenuated and therefore named RMP-IL-18mutE4." (PMID 41488627, 2025). "IL-18 and IL-18BP were expressed in epithelial cells of both tumor and normal ovarian tissues." (PMID 41561739, 2025). "However, intrathecal administration of 11R‐VIVIT or SB239063 reduced tumor‐induced IL‐18 expression." (PMID 39957627, 2025). "Investigating how inflammatory mediators such as IL-1 and IL-18 drive tumor progression could identify new therapeutic targets." (PMID 39578555, 2025). "On one hand, inflammasomes such as NLRP3 and AIM2 can suppress tumorigenesis by enhancing anti-tumor immunity through the activation of caspase-1 and subsequent maturation and release of pro-inflammatory cytokines like IL-1β and IL-18, which recruit and activate immune cells." (PMID 40692785, 2025).
tumor (continued). "Innate immune cells, such as mature dendritic cells (mDCs) and M1-like tumor-associated macrophages (TAMs), secrete cytokines, such as IFN-α, IL-12, IL-18, and TNF, along with chemokines like CXCL9, CXCL10, and CCL21, which effectively suppress tumor angiogenesis." (PMID 40322886, 2025). "Interestingly, engineering CAR-T cells to secrete interleukin-18 (IL-18) can improve their persistence and activity, helping them overcome the tumor immunosuppressive environment and facilitating tumor control." (PMID 41194225, 2025). "In addition to IL-8, other cytokines like IL-15 and IL-18 play pivotal roles in the tumor microenvironment." (PMID 41169398, 2025). "Furthermore, hypoxia signals through HIF1α to inhibit IL18-signaling in NK cells, reducing NK cell anti-tumor activity." (PMID 40849493, 2025). "To evaluate the neuronal mechanism of NFAT1/IL‐18 in the development of pain hypersensitivity induced by tumor inoculation, we evaluated the change in the expression of p‐NR2B, p‐CaMKII, and p‐CREB in the spinal dorsal horn by using spinal blockade of NFAT1 or IL‐18." (PMID 39957627, 2025). "This functional duality underscores IL-18’s capacity to either promote tumour eradication through immune effector cell activation or paradoxically facilitate tumour progression via microenvironmental reprogramming, necessitating precision-based evaluation of its therapeutic modulation." (PMID 40738927, 2025). "However, the intrathecal injection of 11R‐VIVIT or IL‐18 BP significantly reduced the tumor‐induced expression of p‐NR2B, p‐CaMKII, and p‐CREB." (PMID 39957627, 2025). "Monocytes express a wide range of PRPs including TLRs, NLRs, RLRs and CLRs which in glioma TME enable immunosuppression (through IL-10 and TGF-β cytokine release), fuel inflammation (through the secretion of IL-1β and IL-18) and preserve tumor growth (through VEGF, MMPs, and IL-1β expression)." (PMID 41157253, 2025). "Moreover, IL-18 demonstrates pro-inflammatory properties in select malignancies, suppressing tumour progression through angiogenesis inhibition and facilitation of immune cell infiltration within the TME54." (PMID 40738927, 2025). "Antibody-drug conjugates (ADCs) NSCLC-derived tumor cells produce IL-18, which is a key factor in driving type 1 (IFNγ-producing) responses of CD8C T-cells with high levels of IL-18 receptor (IL-18R), which are balanced by dysfunctional T-cells with low levels of IL-18R in ADC NSCLC." (PMID 41179937, 2025). "This approach may work because inflammasome activation can trigger pyroptosis in cancer cells, releasing pro-inflammatory cytokines such as IL-1β and IL-18 that can aid in anti-tumor immune responses." (PMID 40141358, 2025). "They demonstrated that co-armoring with the pro-inflammatory cytokines IL-15 or IL-18 could overcome this limitation, resulting in significantly improved in vivo anti-tumor activity." (PMID 41019052, 2025). "Moreover, phenotypic analysis of CAR T-cells post-injection into tumor-bearing mice revealed increased memory marker and reduced exhaustion marker expression by IL-18-secreting CAR T-cells compared to unarmored CAR T-cells." (PMID 41019052, 2025). "Besides, the expression of IL-1β and IL-18 in tumor tissues was also evaluated by immunohistochemical analysis." (PMID 40604924, 2025). "A previous strategy was used because of the dual nature of Vδ1 T cells (Vδ1 T cells expressing high FITC anti‐human amphiregulin (AREG) levels promote tumor proliferation), which included secondary stimulation and induction with IL‐15/IL‐18 to achieve similar results." (PMID 40112194, 2025). "If the NF‐κB pathway is active, IL‐18 may promote tumor progression, while blocking NF‐κB allows IL‐18 to exert an antitumor effect." (PMID 39969214, 2025).